ICAM1 (intercellular adhesion molecule 1)
Diseases named in the same sentence as ICAM1 in open-access papers (continued):
Sharing a sentence is not in itself a finding about the gene and the disease.
Stroke (continued). "We have also found significant relationships between a greater neuroserpin decrease within the first 24 hours from stroke onset and lower levels of the inflammatory biomarkers ICAM-1 and IL-6 at 24 hours." (PMID 21569344, 2011). "Our previous study on neurovascular protection by S-nitrosylating agents in TBI and stroke shows that GSNO down regulated the expression of inflammatory mediators ICAM-1, ED-1, iNOS, MMP-9, protected the BBB, and improved neurological functions." (PMID 21733162, 2011). "ICAM-1 levels peak 12 hours after stroke onset and are maintained during 24 hours whereas VCAM-1 only peaks after a day in a 1-hour MCAo model." (PMID 21040547, 2010). "We found a novel association between circulating VEGF levels and increased incident DWI‐positive lesions throughout the first year post‐stroke as well as associations between higher levels of P‐Selectin and increased risk for MCI at 1 year and ICAM‐1 and lower CVR." (PMID 40275856, 2025). "However, some studies have failed to establish a significant correlation between soluble ICAM-1 and stroke prognosis." (PMID 40066310, 2025). "Moreover, in stroke, endothelial β2-integrin ligand ICAM-1 influences neutrophil recruitment through the BBB." (PMID 40362673, 2025). "Impressively, TXL could inhibit the stroke‐enhanced expression of adhesion molecules (P‐selectin and ICAM‐1) and chemokines (CCL‐3, CCL‐4, CCL‐5, and CXCL1)." (PMID 37122157, 2023). "However, these approaches have had limited success in clinical trials—e.g., Enlimomab, an anti-ICAM-1 antibody, worsened outcomes in stroke patients." (PMID 37117163, 2023). "Impressively, TXL could inhibit the expression of stroke‐induced upregulated adhesion molecules (P‐selectin and ICAM‐1) and chemokines (CCL‐3, CCL‐4, CCL‐5, and CXCL1)." (PMID 37122157, 2023). "Besides leakage, adhesion proteins such as intercellular adhesion molecule 1 (ICAM1) or vascular adhesion molecule 1 (VCAM1) also change within the BBB after stroke." (PMID 35054890, 2022). "Related studies have found that ICAM‐1 increases in the early exercise after stroke, which may exacerbate the damage of brain tissue." (PMID 34792838, 2022). "Additionally, leukocyte adhesion molecules, VCAM-1 and ICAM-1, are significantly highly expressed post-stroke, thereby prompting leukocyte extravasation." (PMID 36186129, 2022). "As evident from our data, RIC therapy alone in diabetic stroke unexpectedly augmented the inflammatory gene expressions significantly as compared to the stroke control group when analyzed for IL-6 (p = 0.0001), IL-1β (p = 0.0002), iCAM-1 (p = 0.030), and iNOS (p = 0.021) at 6 h post-stroke." (PMID 36290774, 2022). "Moreover, they reported a correlation with stroke severity, with ICAM-1+ EVs (CD105+, CD54+, CD45– (leukocyte marker)) being most strongly correlated with infarct volume and endoglin+ EVs (CD105+, CD41a–, CD45–) correlating with long-term clinical outcome." (PMID 36009857, 2022). "Whether VCAM-1 and ICAM-1 imaging methods provide differential information on stroke, pathophysiology remains to be explored." (PMID 34065179, 2021). "However, the effects of 2 h of hypothermia, in terms of reduction of cellular infiltration, phagocytic potential and ICAM-1 expression, were still evident at 3 days post induction, in a rodent stroke model." (PMID 31924278, 2020). "Animal study also showed that SO2 elevated the levels of cyclooxygenase-2, interleukin-1b, tumor necrosis factor-a, intercellular adhesion molecule-1 mRNA and protein, which might also play a role in the development of stroke." (PMID 32085727, 2020). "As ICAM-1 levels peak at 12–48 h post-stroke, they are ideal targets for the acute phase." (PMID 31281252, 2019). "HIV infection was independently associated with high levels of ICAM-1 (OR = 3.6, 95% CI: 1.3–10.6, p = 0.018) in controls but not in stroke cases even after excluding patients with a viral load >1,000 RNA copies/mL (OR = 4.1, 95% CI: 1.3–13.1, p = 0.017)." (PMID 30697583, 2019).
Stroke (continued). "The presence of neutrophils relies upon intercellular adhesion molecule 1 (ICAM-1) expression and is associated with increased secretion of proteolytic enzymes and worsened post-ischemic CNS injury in rodent models of stroke." (PMID 29895321, 2018). "Furthermore, we assessed potential interfering effects of ICAM-1-targeted contrast agent on post-stroke lesion growth." (PMID 28509283, 2017). "We explored to what extent MR contrast agent targeted to intercellular adhesion molecule-1 (ICAM-1) could detect endothelial- and leukocyte-associated ICAM-1 expression at different stages after experimental stroke." (PMID 28509283, 2017). "In addition, we assessed possible interfering effects of ICAM-1-targeted MPIO on post-stroke lesion development." (PMID 28509283, 2017). "However, the amount of ICAM-1-positive vessel-like structures as well as MPIO presence were reduced at this stage compared to the earlier post-stroke phases, which is in agreement with the MRI findings." (PMID 28509283, 2017). "PARP suppression has been shown to diminish edema, preserve the tight junction protein, occludin, and decrease expression of the adhesion molecule, ICAM-1, in animal models of stroke, traumatic brain injury, meningitis, and MS, reducing leukocyte infiltration and brain inflammation." (PMID 27677851, 2016). "One could speculate that the known pro-inflammatory state in hypertensives increases leukocyte ICAM-1 expression and thus contributes to increased post-stroke inflammation, but this assumption warrants further investigations." (PMID 26640428, 2015). "This may reflect a more profound effect of EP1 knockout compared to a pharmacological antagonist and/or differences between species in the mechanism(s) responsible for the increases in ICAM-1 levels in response to stroke." (PMID 26648273, 2015). "Experimentally, s-ICAM-1 is upregulated after embolic stroke." (PMID 22397464, 2012). "The detected high ICAM-1 level, an important marker of neuroinflammation, is associated with low levels of EPC in early stroke, which supports our hypothesis that early inflammation inhibits neovascularization." (PMID 21871109, 2011). "Also, ICAM‐1 has a close relationship between hypertensive state and stroke risks of females." (PMID 34792838, 2022). "Notably, dBET1 significantly attenuated the sharp upregulation of ICAM-1 induced by stroke." (PMID 35761277, 2022). "ICAM-1, as a cell-surface glycoprotein member of the immunoglobulin superfamily, participates in the trafficking and adhesion of leukocytes to activated ischemia endothelia in stroke, so ICAM-1-induced intervention has become a promising therapeutic strategy against stroke." (PMID 33927611, 2021). "However, in terms of the major adverse cardiovascular events, VCAM-1 concentration is significantly associated with cardiovascular mortality in type 2 diabetes patients, and circulating levels of soluble VCAM-1, ICAM-1 are shown to be elevated in diabetic patients with stroke." (PMID 31550292, 2019). "Likewise, although there is lack of evidence in brain distribution of Tetrandrine (TTD), a large-molecule natural chemical product purified from Fourstamen stefania root, it is certified to inhibit neutrophil recruitment by downregulating the expression of ICAM-1 and improve stroke outcomes." (PMID 27688603, 2016). "Elevated levels of ICAM-1 and VCAM-1 have been detected in the blood and infarct regions of stroke patients." (PMID 40066310, 2025). "Nonetheless, to the authors’ knowledge, this represents the most comprehensive systematic review of blood-based protein biomarkers for stroke: MMP-9, TNF-alpha, VCAM-1, ICAM-1, E-Selectin, P-Selectin, L-Selectin, NSE, GFAP, S100, S100B, BNP, and NT-proBNP." (PMID 39091977, 2024). "Clustering analysis of DEGs in male and female stroke brains revealed that MMP-3 KO decreased expression of genes that belong to the adhesion and leukocyte extravasation pathway such as Esam, Icam1, Icam2, Mcam1, and Pecam1." (PMID 39000490, 2024).
Stroke (continued). "Intracranial injection of MSCs was reported to prevent BBB leakage via regulation of intercellular adhesion molecule-1 (ICAM-1) and MMP-9 in a mice model of stroke." (PMID 37605722, 2023). "Stroke triggered BBB breakdown and MMP-9 activation, neutrophil infiltration, and increased expression of ICAM-1, which were profoundly attenuated by dBET1." (PMID 35761277, 2022). "Meanwhile, stroke-induced BBB disruption, increased MMP-9 levels, neutrophil infiltration, and increased ICAM-1 were significantly attenuated by dBET1 treatment." (PMID 35761277, 2022). "A stronger elevation of VCAM-1 and ICAM-1 expression in cerebellar endothelial cells suggested a higher interaction between inflammatory cells and vessels, which might lead the cerebellum to be more sensitive to neutrophils, the fastest-accumulated cells in infarcted regions after stroke." (PMID 35592334, 2022). "The alleviated systemic inflammation leads to downregulation of ICAM-1, VCAM-1, and MMP-9 in the brain, which preserves the cerebral endothelial glycocalyx and protects the BBB, resulting in protection against stroke injury." (PMID 34612696, 2021). "The expression of endothelial cell adhesion molecules (CAMs) such as intercellular CAM-1 (ICAM-1) can be studied in our NVU on-a-chip model at baseline and after mimicking stroke or other neurological disorders." (PMID 34906183, 2021). "In an experimental setting, IFN-β downregulated ICAM-1 expression on cerebral endothelial cells and attenuated BBB disruption and neutrophil infiltration in a rat model of stroke, thereby reducing infarct volume." (PMID 35008440, 2021). "Compared to controls, stroke patients had significantly higher VEGF-A and VCAM-1 at <8 h that remained elevated at 72 h, with significantly higher VEGF-A at <8 h; ICAM-1 was significantly increased at <8 h, while S100B and E-selectin were unchanged." (PMID 32595585, 2020). "In the logistic regression analysis, the adjusted OR for having high plasma levels of ICAM-1 was 3.6 (95% CI: 1.3–10.6, p = 0.018) for the profile “HIV-positive controls” and 1.2 (95% CI: 0.4–4.0, p = 0.772) for the profile “HIV-positive stroke”." (PMID 30697583, 2019). "At post-stroke day 3, detected MPIO were not only present at the ICAM-1-positive vasculature but also co-localized with vasculature-confined CD45-positive leukocytes." (PMID 28509283, 2017). "At post-stroke days 1 and 2, MPIO were abundantly present in the lesion area and strictly confined to ICAM-1-positive structures which displayed vascular morphology." (PMID 28509283, 2017). "For instance, there was evidence of a synergistic interaction between ICAM1 rs281432 and urinary As on CVD (p = 0.014) and stroke (p = 0.005)." (PMID 25575156, 2015). "Increase of adhesion molecules expression (such as ICAM-1, VCAM-1, E-selectin and so on) has been described after stroke." (PMID 24946684, 2014). "The most important finding in the study is the link between high ICAM-1 and low levels of circulating CD133+CD34+ EPC in early stroke." (PMID 21871109, 2011). "In addition, it was also able to significantly inhibit PAF, IL-6, TNF-α, ICAM-1, and VCAM-1, which significantly improved cognitive function, attenuated anxiety-like behaviors, and promoted post-stroke brain function and motor recovery in stroke rats." (PMID 40837062, 2025). "Similarly, genes involved in integrin cell surface interactions including Itga10, Itgb3, Vcam1, Itgb1, Itgae, Itgb7, Itga1, Itga5, Icam1, Itgb2, Pecam1, and Icam2 were depleted in male MMP-3 KO stroke brains." (PMID 39000490, 2024). "In the early stages of stroke, neutrophils are activated and they attach to the endothelium owing to the expression of endothelial adhesion molecules, including PSGL-1, MAC-1, CD11a, and ICAM-1." (PMID 36186129, 2022). "One prominent example is a recent report elegantly showing that when using knockout mice for stroke experiments, which have a complete deletion of the ICAM-1 gene, no protection is observed." (PMID 35140676, 2021).
Stroke (continued). "The Chongqing Stroke Study reported that ischemic stroke patients with neurological deterioration had higher levels of soluble ICAM1 but not soluble VCAM1 compared to patients without neurological deterioration based on the NIHSS." (PMID 33971895, 2021). "Stroke patients with unfavorable outcomes had a lower proportion of small-sized HDLs and increased plasma levels of E-selectin (SELE) and the intercellular adhesion molecule 1 (ICAM1)." (PMID 32708891, 2020). "We now show in vivo that mice lacking IL-1R1 on brain endothelial cells exhibit reduced cerebrovascular expression of ICAM-1 and VCAM-1 that is accompanied by a marked reduction in the number of neutrophils infiltrating the brain in response to stroke, supporting our previous in vitro findings." (PMID 30453020, 2019). "Using a cross-sectional design, we measured plasma levels of intercellular adhesion molecule-1 (ICAM-1), plasminogen activator inhibitor-1 (PAI-1), vascular endothelial growth factor (VEGF), and soluble thrombomodulin (sTM) in stroke patients and controls, stratified by HIV status." (PMID 30697583, 2019). "To conclude, this study shows that molecular MRI with αICAM-1-MPIO offers a unique approach for in vivo imaging of endothelial ICAM-1 expression and vascular leukocyte adhesion after experimental stroke, without significantly affecting lesion development." (PMID 28509283, 2017). "Leukocyte AM expression was not influenced by hypertension in naive rats, but by stroke: SHR exhibited a significantly increased MFI of ICAM-1 on myeloid leukocytes, whereas VCAM-1 and CD62P remained unchanged." (PMID 26640428, 2015). "Neither hypertension nor stroke had an impact on the endothelial expression of ICAM-1 and VCAM-1 at day 4 after PT." (PMID 26640428, 2015). "In contrast, ICAM-1 expression on endothelial cells was not changed 4 days after stroke, possibly because responsive endothelial AM expression peaks earlier." (PMID 26640428, 2015). "Previous experimental studies showed a plateau in expression of ICAM-1 by endothelial cells after TNF-α activation between days 1-3, and after the stroke onset a persistency in soluble ICAM-1 levels on days 1, 3 and 14 was detected; our follow-up data on day 3 is in line with these findings." (PMID 21871109, 2011). "Predictors of adverse stroke outcome include TNF-α, ICAM-1, and IL-6." (PMID 20700422, 2010). "Therefore, we were interested the expression of ICAM-1, MCP-1, and VCAM-1 in the astrocytes of SHRSP/IZM rats during stroke statuses such as H/R and TNF-α stimulation." (PMID 20700422, 2010). "The increases in ICAM-1 and VCAM-1 after stroke are influenced by IL-1β and TNF-α." (PMID 21040547, 2010). "Interestingly, ONO-AE1-259-01 has been suggested to elevate cAMP and inhibit expression of inflammatory molecules such as ICAM-1 and B7.2 (CD86), and such inflammatory molecules affect stroke outcomes." (PMID 20615245, 2010). "In particular, injection of anti-ICAM-1 is not an effective treatment for ischemic stroke, indeed, may significantly worsen the stroke outcome." (PMID 36247764, 2022). "In contrast, an anti-ICAM-1 functionalized MPIO (ICAM-MPIO) with a size of approximately 1 μm bound specifically to TNF-stimulated brain endothelial cells in vitro, and showed T2 hypointense brain areas 1 hour after induction of the transient MCAO stroke model in vivo." (PMID 25525560, 2014). "Metformin down-regulated ICAM-1 in an AMPK-dependent manner, which could effectively prevent ischemia-induced brain injury by alleviating neutrophil infiltration, suggesting that metformin is a promising therapeutic agent in stroke therapy." (PMID 25315906, 2014). "Further, serum levels of intercellular adhesion molecule-1 (ICAM-1) and monocyte chemoattractant protein-1 (MCP-1) are high in patients with ischemic stroke and myocardial infarction, which might be interpreted as a stroke-induced increase in inflammatory events." (PMID 23326018, 2012).
Stroke (continued). "Brain endothelial expression of intercellular adhesion molecule 1 (ICAM-1), vascular cell adhesion molecule 1 (VCAM-1), and P-selectin (CD62P) was neither increased by hypertension nor by stroke." (PMID 26640428, 2015).